MX2 (MX dynamin like GTPase 2)
Diseases named in the same sentence as MX2 in open-access papers (continued):
Sharing a sentence is not in itself a finding about the gene and the disease.
influenza (10 papers, 2010 to 2024). An acute viral infection of the respiratory tract, occurring in isolated cases, in epidemics, or in pandemics; it is caused by serologically different strains of viruses (influenzaviruses) designated A, B, and C, has a 3-day incubation period, and usually lasts for 3 to 10 days. "In rodents, Mx1 and Mx2 localise to the nucleus and cytoplasm, respectively, and this correlates with their antiviral profile; Mx1 inhibits influenza and other viruses that replicate in the nucleus whereas Mx2 inhibits viruses that replicate in the cytoplasm." (PMID 29215570, 2017). "It is noteworthy that Irf7 and Mx2 are upregulated upon whole virion influenza vaccine which showed leukopenia in treated animals, and are downregulated upon whole cell pertussis vaccine which showed leukocytosis in treated animals." (PMID 25909814, 2015). "Other studies on the human MxA and rat Mx2 proteins showed that translocation of these proteins from their natural cytoplasmic location to the nucleus enhanced or revealed, respectively, anti-influenza activities." (PMID 20808435, 2010). "Interestingly, we identified Irf7 and Mx2 (Grade 1) as biomarkers not only for influenza vaccine, but also for pertussis vaccine." (PMID 25909814, 2015). "The MDCK cells do not have a robust Mx1 and Mx2 response to influenza and this has been correlated with changes in the polymerase and NS segments." (PMID 32925936, 2020). "Thirdly, the rat Mx2 protein has no anti-influenza activity when in its natural cytoplasmic location, but gains this ability upon translocation to the nucleus." (PMID 20808435, 2010). "However, in our models of infection, we were unable to detect changes in the expression of interferon genes or early interferon-stimulated genes such as Mx2 after PGZ treatment of influenza-infected animals (data not shown)." (PMID 36052067, 2022). "Finally, MDCK cells do not have a robust Mx1 and Mx2 response to influenza." (PMID 32925936, 2020).
glioblastoma (6 papers, 2018 to 2023). The most malignant astrocytic tumor (WHO grade IV). "Here we evaluated the levels of oHSV-1 multiplication in various tumor cell lines and showed that glioblastoma cell line A172 had the lowest virus yields but intrinsically accumulated the highest levels of Mx2 protein." (PMID 34707174, 2021). "Wang and their colleagues found that the MX2 could suppress the glioblastoma progression through ERK/P38/NF-κB signaling." (PMID 37063301, 2023). "It is interesting to notice that MX2 (Hsa21 gene) over-expression is involved in the suppression of cell proliferation, migration and invasion in glioblastoma cells but also that the MX2 gene has an important role in the morphology and function of the mitochondrial membrane." (PMID 33933170, 2021). "To assess the impact of MxB expression on HSV-1 infection, we transfected T98G glioblastoma cells known to express high levels of MxB in response to type I IFN46 with non-targeting control small interfering RNA (siRNA) (siNT) and MX2-targeting siRNAs (siMxB 3'-untranslated region (UTR), siMxB #1)." (PMID 29773792, 2018). "Although A172, D54, and DU145 are described as human glioma cell lines, they have different mutations or overexpression of some genes, and even various tumorigenicity, which may be the explaination for the different roles of Mx2 plays in these 3 glioblastoma cell lines." (PMID 34707174, 2021). "A recent study showed that over-expression of MX2 reduced cell proliferation, migration, and invasion via ERK/P38/NF-κB signalling pathway in glioblastoma cells." (PMID 36329447, 2022). "Hence, MX2 is a potential biomarker that may be used to diagnose glioblastoma." (PMID 34961819, 2021).
AIDS (5 papers, 2019 to 2024). A syndrome resulting from the acquired deficiency of cellular immunity caused by the human immunodeficiency virus (HIV). "It has been shown that MX2 is a cell autonomous anti-HIV-1 resistance factor whose purposeful mobilization may serve as a novel approach for the treatment of HIV/AIDS." (PMID 35003257, 2021). "Although the role of MX2 in various immune-related diseases, such as AIDS, hepatitis C, and RA, has been previously studied, the relationship between MX2 and SLE has not been thoroughly investigated." (PMID 36059547, 2022).
HCMV infection (4 papers, 2019 to 2025). "Several ISGs, including IFIT1, IFIT2, IFIT3, Mx1, Mx2, CXCL10 and ISG15 were found to be upregulated transcriptionally following HCMV infection independently of type I IFN-initiated JAK-STAT signaling, but dependent on intact IRF3 signaling." (PMID 30871003, 2019). "Induction of the IFN-independent ISG viperin during HCMV infection is known to be induced by either IRF3 or IRF1, binding directly to its promoter, and this may also be the mechanism of IFIT1, IFIT2, IFIT3, CXCL10, Mx1, Mx2 and ISG15 upregulation." (PMID 30871003, 2019).
glioma (3 papers, 2021 to 2025). A benign or malignant brain and spinal cord tumor that arises from glial cells (astrocytes, oligodendrocytes, ependymal cells). "Moreover, MX2 overexpression markedly reduced the proliferation, migration, and invasion of glioma cells." (PMID 39233332, 2024). "Meanwhile, IRF7, MX2, and OAS1 are key mediators in immune regulatory pathways, and their overexpression may facilitate immune evasion in gliomas." (PMID 40365337, 2025).
herpesvirus infection (3 papers, 2019 to 2025). "None of the differentially regulated genes were linked to antiviral immunity associated with herpesvirus infections (for example, MX2, IFI16, CGAS, IFITs and OASs32,82–84), indicating that the anti-VZV function of NPHP4 is probably independent of the innate immune defence." (PMID 40739040, 2025). "Mx2 has been reported that could block herpesvirus infection by interfering with the translocation of genomic viral DNA into the nucleus." (PMID 34707174, 2021).
autoimmune disease (2 papers, 2020 to 2022). A disorder resulting from loss of function or tissue destruction of an organ or multiple organs, arising from humoral or cellular immune responses of the individual to their own tissue constituents. "IFIT5, IFI16 and MX2, interferon-stimulated genes, both nuclear transcriptional factors, were found to be upregulated in other autoimmune diseases but not in JDM." (PMID 32110496, 2020).
colorectal cancer (2 papers, 2020 to 2022). A primary or metastatic malignant neoplasm that affects the colon or rectum. "Among genes with downregulated methylation in HL60/MX2, ERCC6 was directly involved in regulating the response to 5-FU chemotherapy in colorectal cancer." (PMID 35865472, 2022).
Down syndrome (2 papers, 2014 to 2024). "For example, four IFN receptor genes (IFNAR1, IFNAR2, IFNGR2, and IL10RB) and two IFN-stimulated genes (MX1 and MX2) are triplicated in Down syndrome, and individuals with Down syndrome exhibit hypersensitivity to type I IFN (IFN-I)." (PMID 38540156, 2024).
endometrial cancer (2 papers, 2021 to 2022). Primary or metastatic malignant neoplasm involving the endometrium (mucous membrane that lines the endometrial cavity). "Likewise, in a previous study, MX2 was proven to be involved in the construction of a model associated with neutrophils in endometrial cancer." (PMID 36059547, 2022).
leukaemia (2 papers, 2005 to 2017). "We examined the expression levels of phosphorylated p38α protein in MX2‐resistant leukemia cells compared with sensitive parent cells." (PMID 28596837, 2017). "The analysis identified 10,515 genes as differentially expressed between MX2‐sensitive and ‐resistant leukemia cells." (PMID 28596837, 2017). "We next examined the p38 kinase activity in MX2‐resistant leukemia cells compared with sensitive parent cells." (PMID 28596837, 2017). "We next examined the p38α mRNA expression in MX2‐resistant leukemia cells compared with sensitive parent cells." (PMID 28596837, 2017). "Using siRNAs (siRNA1, 2, 3) to knock down p38α effectively decreased the p38α mRNA and protein expression in MX2‐resistant leukemia cells (K562/MX2, BALL/MX2)." (PMID 28596837, 2017). "Our results suggest that adding p38 MAPK inhibitors will decrease the resistance to MX2 in MX2‐resistant leukemia cell lines by partially decreasing p38 activity." (PMID 28596837, 2017). "The specific inhibitors of p38 MAPK, SB203580 and SB202190, effectively decreased the levels of phosphorylated p38α protein in MX2‐resistant leukemia cells (K562/MX2, BALL/MX2)." (PMID 28596837, 2017). "In order to elucidate the cellular target of and resistance mechanisms against MX2, we established an MX2-resistant human leukaemia cell line (K562/MX2), which is eight-fold more resistant to MX2 than the parental K562 cell line (K562/P)." (PMID 15798770, 2005). "To investigate the mechanisms of resistance to MX2, we established an MX2-resistant phenotype (K562/MX2) of the human myelogeneous leukaemia cell line (K562/P), by continuously exposing a suspension culture to increasing concentrations of MX2." (PMID 15798770, 2005). "Inhibition of p38 MAPK restored the sensitivity to MX2 in MX2‐resistant leukemia cell lines." (PMID 28596837, 2017). "Using specific inhibitors of p38 MAPK, SB203580 and SB202190, effectively decreased the p38 kinase activity in MX2‐resistant leukemia cells (K562/MX2, BALL/MX2), but SB202474 (negative control) did not decrease the activity." (PMID 28596837, 2017). "Inhibition of p38 MAPK activation by pharmacological inhibitors increased the cytotoxicity of MX2 in MX2‐resistant leukemia cell lines, but not in MX2‐sensitive cell lines." (PMID 28596837, 2017).
leukopenia (2 papers, 2015 to 2022). "The combination model of MX2 and IFIH1 could determine high-risk patients with leukopenia, and the combination model of IFIT3 and IFIH1 had a definite diagnostic accuracy in detecting fever among patients with SLE." (PMID 35757684, 2022). "The combination model of MX2 and IFIH1 was also good at determining the leukopenia group in patients with SLE, and the regression model was 5.6248 + −2.5919 × MX2 + 2.0122 × IFIH1 (AUC = 0.811)." (PMID 35757684, 2022).
multiple sclerosis (2 papers, 2023 to 2024). A progressive autoimmune disorder affecting the central nervous system resulting in demyelination. "Likewise, in the brain tissue of multiple sclerosis patients, MX2 protein was detected in most cases compared to controls." (PMID 37184765, 2023).
Obesity (2 papers, 2021 to 2025). Accumulation of substantial excess body fat. "We observed a significant induction in the levels of C3, CP enzyme, growth factor IGFBP4, and cytokine CXCL10 and interferon signaling-related genes including (IFNβ, ISG15, MX2 and OASL2), some of which have been recognized for their role either in obesity or inflammation." (PMID 33672392, 2021).
parasite infection (2 papers, 2016 to 2022). "C57BL/6 mice infected with N67 parasite induced a strong IFN-I response, including increased expression of genes such as Cd40, Isg15, Isg20, Ifit2, Mx1, Mx2, Ddx58, and Usp18 genes, leading to suppression of N67 parasitemia." (PMID 27716849, 2016).
rheumatoid arthritis (2 papers, 2022 to 2024). A chronic, systemic autoimmune disorder characterized by inflammation in the synovial membranes and articular surfaces. "These genes, OAS2, MX1, and MX2, have been linked to the response of immunological pathways in rheumatoid arthritis and periodontitis." (PMID 38323815, 2024). "Recently, MX2 has also been identified as an immune-related marker in rheumatoid arthritis (RA)." (PMID 36059547, 2022).
type 1 diabetes (2 papers, 2016 to 2021). "The islet RNA expression analysis identified two genes (ADAR and MX2) that were novel in having a direct relation to type 1 diabetes, out of 19 dysregulated genes." (PMID 33973017, 2021). "MX2 expression was increased by 24% in individuals with longstanding type 1 diabetes (p = 3.80 × 10−2, 95% CI −0.18, −0.004)." (PMID 33973017, 2021). "We found that MX1 was upregulated in new-onset type 1 diabetes and that MX2 was upregulated in longstanding type 1 diabetes as well as having two eQTL SNPs." (PMID 33973017, 2021). "Alterations in IFN-stimulated gene patterns (including in Ifit, Mx2, Cxcl10) and/or in Jak/STAT activity, a main IFN-dependent pathway, cause a failure in immunological tolerance resulting in T cell-mediated autoimmune pathologies (e.g., type I diabetes)." (PMID 27256343, 2016). "The majority of ISGs were upregulated in individuals with new-onset type 1 diabetes; however, in longstanding type 1 diabetes ADAR was downregulated and MX2 was upregulated (both ISGs)." (PMID 33973017, 2021).
age-related macular degeneration (1 paper, 2019). Age-related loss of vision in the central portion of the retina (macula), secondary to retinal degeneration. "In another study, treatment of retinal pigment epithelium (RPE) cells with amyloid-β1-40, a known inflammatory trigger in Age-related macular degeneration (AMD) caused a significant induction of inflammatory genes such as BST2, STAT1, RSAD2, MX2, OAS1&2, IFNL44 and LXN43." (PMID 30914656, 2019).
Aicardi-Goutières syndrome (1 paper, 2021). "We next examined baseline gene expression (qPCR) of archetypal interferon stimulated genes (ISGs) IFI27, USP18, MX1, OASL, IRF7, and MX2, and those ISGs found highly expressed in PBMCs from the type 1 interferonopathy, Aicardi-Goutières syndrome (AGS) patients (IFI27, ISG15, IFI44L, and RSAD2)." (PMID 33746960, 2021).
arterial hypertension (1 paper, 2023). "The upregulation of the Mx1 and Mx2 genes has also been linked to inherited stress-induced arterial hypertension in rats." (PMID 38045685, 2023).
atopic dermatitis (1 paper, 2025). "Variation in MX2 has also been linked to wool and skin traits in sheep and increased expression of MX2 has been found in canine atopic dermatitis." (PMID 40971676, 2025).
breast carcinoma (1 paper, 2025). "Previous studies have found that when the expression of the tumor suppressor gene circ_ATAD3B is increased, it promotes the expression of miR-570-3p and inhibits the expression of MX2, thereby inhibiting the proliferation of breast cancer." (PMID 40688112, 2025).
cervical (1 paper, 2020). "MX2 also has a potential function in cervical carcinogenesis." (PMID 33121134, 2020).
co-infection (1 paper, 2020). "The co-infection allowed observation of multiple genes involved in the obstruction of the viral life cycle within the host such as MX1,MX2, OASL, OAS2, heat shock protein family A (Hsp70) member 8 (HSPA8), and radical S-adenosyl methionine domain containing 2 (RSAD2)." (PMID 33187194, 2020).
colitis (1 paper, 2021). Inflammation of the colon. "Since IFN signaling seems to be critical for the colonic recovery from the DSS-induced damage, we used Mx2-Luciferase (Mx2-Luc) reporter mice to evaluate the timing of IFN signaling during acute DSS-induced colitis." (PMID 33976143, 2021).
dermatomyositis (1 paper, 2021). Dermatomyositis (DM) is a type of idiopathic inflammatory myopathy characterized by evocative skin lesions and symmetrical proximal muscle weakness. "In conclusion, a total of 3 genes associated with the development of dermatomyositis—MX2, OAS1, and OAS2—were identified in this study through a series of information biology analyses, which are expected to be biomarkers or drug targets to some extent for the diagnosis of dermatomyositis." (PMID 35003257, 2021). "In the present study, MX2 is also expected to be a potential target for dermatomyositis treatment." (PMID 35003257, 2021). "The results showed that MX2, OAS1, and OAS2 were significantly upregulated in the GSE11971 and GSE142807 datasets compared to normal samples in dermatomyositis samples." (PMID 35003257, 2021).
E. coli infection (1 paper, 2017). "For comparison, E. coli infection up-regulated the expression of MX2 by 1.8 fold during the 3rd h of infection." (PMID 28684793, 2017).
embryonal carcinoma (1 paper, 2015). A non-seminomatous malignant germ cell tumor characterized by the presence of large germ cells with abundant cytoplasm resembling epithelial cells, geographic necrosis, high mitotic activity, and pseudoglandular and pseudopapillary structures formation. "Unfortunately, endogenous MX2 is expressed at detectable levels in none of the cell lines we use for our retrotransposition assay (293T, HeLa, or human embryonal carcinoma 2102Ep cells) and is induced by IFN in HeLa cells only." (PMID 26001115, 2015).
inflammatory skin disease (1 paper, 2021). Inflammatory skin disorders covers a broad category that includes many conditions ranging in severity, from mild itching to grave medical health complications These disorders are common in people of all ages and races. "Likewise, under AZ(−) conditions, THDC increased expression of genes belonging to the STAT1-57 module (P < 0.01), which is a set of genes activated by interferon signaling with elevated expression in inflammatory skin disease (e.g., MX2, IFIT3, IFI44)." (PMID 34445461, 2021).
legionellosis (1 paper, 2021). Any disease caused by Legionella bacteria. "Interfering a series of human diseases pathways including legionellosis, toxoplasmosis, and measles and some key factors such as MAFF, HSPA1A, HSPA1B, AOC1, and MX2, high doses of moxa smoke influenced the function of rat lungs." (PMID 34961819, 2021).
lung adenocarcinoma (1 paper, 2016). A carcinoma that arises from the lung and is characterized by the presence of malignant glandular epithelial cells. "With higher occurrences, the correlation of differential gene expression and aberrant DNA methylation of AGR2, CDH13, and MX2 have been reported relevant to lung adenocarcinoma." (PMID 27610367, 2016).
mental disorder (1 paper, 2022). A disease that has its basis in the disruption of mental process. "Eight genes are implicated in viral (SEC14L1, JMJD6, SRSF2, TMPRSS2, MX1, MX2) or bacterial (COL8A1, SPIRE1) infections, seven genes (MFSD11, METTL23, CTTNBP2, BACE2, IMPA2, MPPE1 and GNAL) are involved in mental disorders and one gene (MGAT5B) is related to the Golgi complex." (PMID 35581286, 2022).
neuroblastoma (1 paper, 2017). Neuroblastoma (NB) is the most common solid, extracranial childhood tumor. "Studies of human SH-SY5Y neuroblastoma cells transfected with human PRNP displayed a significantly dampened response (MX2 expression) to a low-level IFN-α stimulation, compared with untransfected cells that are virtually devoid of PrPC." (PMID 28651013, 2017).
prostate carcinoma (1 paper, 2016). A carcinoma that arises from epithelial cells of the prostate gland. "For example, the ISGs MX1 and MX2 show deep co-deletions in 14 % of prostate cancer patients." (PMID 27366948, 2016).
prostate tumours (1 paper, 2019). "MX2 expression in primary prostate tumors was evaluated using immunohistochemistry." (PMID 30914795, 2019). "Analysis of MX2 expression in primary prostate tumours, normal prostate tissue and normal tissue adjacent to tumours (NAT) revealed high levels of MX2 expression only in NAT." (PMID 30914795, 2019). "Correspondingly, immunohistochemical analysis of prostate tumours and normal prostate tissue revealed that MX2 protein is only present in the stroma surrounding prostate tumours and not in normal prostate tissue." (PMID 30914795, 2019). "Furthermore, while neither MX2 protein nor RNA was detected in prostate tumors, or indeed in normal prostate cells in the absence of cancer, both are detected at high levels in ‘normal’ stromal cells adjacent to tumors." (PMID 30914795, 2019).
Splenomegaly (1 paper, 2018). Abnormal increased size of the spleen. "Among predicted target genes of these up-regulated miRNAs, genes related to IFN-α and β production as well as the innate immune response (e.g., Irf7, Dhx58, Oas1b, Mx2) were down-regulated in PPVL-induced splenomegaly." (PMID 30573742, 2018).
uterine infection (1 paper, 2022). "When comparing all four studies, a total of 24 genes were consistently upregulated by pregnancy regardless of previous uterine infection, including DKK1, MX1, MX2, STAT1 and a number of interferon stimulated genes." (PMID 35358206, 2022).